MFN2 (mitofusin 2)
Diseases named in the same sentence as MFN2 in open-access papers (continued):
Sharing a sentence is not in itself a finding about the gene and the disease.
lung carcinoma (24 papers, 2014 to 2025). "Both breast and lung cancer patients with low MFN2 expression were associated with poor prognosis as compared to patients with high expression of MFN2." (PMID 28176801, 2017). "Moreover, MFN2 overexpression suppress cancer progression, while low expression of this mitofusin is associated with poor prognosis in breast and lung cancer." (PMID 36739349, 2023). "In lung cancer cells, interventions that sustain mitochondrial fusion (whether caused by inhibiting Drp1 or augmentation of Mfn2) reduce cell proliferation and increase spontaneous apoptosis." (PMID 37508561, 2023). "We investigated the expression of mitofusin-2 (Mfn2), a mitochondrial GTPase that may be related to chemoresistance, and found that Mfn2 expression was lower in human cisplatin-resistant lung carcinoma A549/DDP cells than in cisplatin-susceptible A549 cells." (PMID 30410558, 2018). "On the other hand, MFN2 overexpression exerts positive function in lung cancer cells and HepG2 cells." (PMID 40661148, 2025). "The downregulation of MFN2 in PAH as well as lung cancer, in part, appears to be tied to increased proteasomal degradation, which is triggered by PINK1-induced serine-442 MFN2 phosphorylation." (PMID 36819102, 2023). "For instance, lung cancer samples obtained from patients show the same pattern of increased Drp1 and decreased MFN2 levels compared with tissue adjacent to healthy lung tissue." (PMID 37669960, 2023). "Similar apoptosis induction occurs in various lung cancer cell lines when inhibiting Drp1; using siDrp1, small molecule Drp1 inhibitors such as mdivi-1 or drpitor1a; or augmenting Mfn2." (PMID 37508561, 2023). "In lung cancer, MFN2 has also been demonstrated to inhibit Rictor, a subunit of the mTORC2 complex, which prevents AKT1 phosphorylation and subsequent cytoskeletal reorganization for cell division." (PMID 36819102, 2023). "Similar results have been reported in gastric and lung cancer, in which Mfn2 overexpression has also been found." (PMID 35327574, 2022). "Targeting inhibition of mitofusin-2 (Mfn-2) and/or Drp1 impairs mitochondrial fission and cell cycle progression, preventing lung cancer cell proliferation." (PMID 35230214, 2022). "Similar phenomenon was observed on MFN2 (mitochondrial GTPase mitofusin-2) knockout cells in lung cancer via CRISPR/Cas9." (PMID 34598686, 2021). "Human lung cancer cell lines or lung tumor tissue samples all exhibit an imbalance of Drp1/Mfn2 expression, which facilitates a state of mitochondrial fission." (PMID 31936883, 2020). "The increased mitochondrial fission, which is mediated by upregulated Drp1 and downregulated Mfn2, has been observed in lung cancer cells." (PMID 30323195, 2018). "Human lung cancer cell lines exhibit an imbalanced expression level of Drp1/Mfn2, which promotes a state of mitochondrial fission." (PMID 28402939, 2017). "Support for the role of mitochondrial dynamics in cancer progression comes from a study in lung cancer, where it was revealed that human lung cancer cell lines have imbalanced expression levels of Drp1/Mfn-2 that promote a state of fragmented mitochondria." (PMID 24632851, 2014). "Indeed, MFN2 overexpression, along with Drp1 knockdown, increases apoptosis in lung cancer cells, reducing their proliferation." (PMID 40274776, 2025). "In lung cancer, impaired fusion and enhanced fission caused by DRP1 activation of MFN2 inhibition fragment the mitochondrial network, which may facilitate mitosis." (PMID 36739349, 2023). "Likewise, in lung cancer cell lines (H358, A549 and H1993), mitochondrial fission is increased due to the combined effects of increased Drp1 and decreased Mfn2 expression." (PMID 37508561, 2023). "Moreover, Mfn2 overexpression reduced lung cancer growth, as well as the migration and invasion of breast cancer cell lines." (PMID 32548570, 2020).
lung carcinoma (continued). "Additionally, the expression of Mfn2 in lung cancer is lower than that in normal tissues, and overexpression of Drp1/Mfn2 can affect mitochondrial dynamics and inhibit the proliferation of lung cancer cells." (PMID 32587855, 2020). "However, whether UCP4 plays a role in LUAD and whether UCP4 and MFN2 coregulate mitochondrial function in lung cancer remain unknown." (PMID 36877954, 2023). "Interestingly, Mfn2 gene therapy, which involves the insertion of genetic material (DNA) into the cells to restore Mfn2 gene expression, has been reported to reduce the proliferation of A549 human lung cancer cells by promoting apoptosis." (PMID 32548570, 2020). "However, overexpression of Mfn2, Drp1 knockdown, or Drp1 inhibition in lung cancer cells could restore mitochondrial network formation and result in an obvious increase in spontaneous apoptosis and reduction of cancer cell proliferation." (PMID 31936883, 2020). "In conclusion, our data suggest not only a potential role of MFN2 and UCP4 in co‐regulating calcium homeostasis in lung adenocarcinoma but also their potential use as therapeutic targets in lung cancer." (PMID 36877954, 2023). "Taken together, our data demonstrate that MFN2 and UCP4 cooperate in the regulation of ATP and intracellular calcium homeostasis in lung cancer." (PMID 36877954, 2023). "Mfn2 deficiency, which contributes to mitochondrial fragmentation in PAH and lung cancer, results in part from increased proteasomal degradation triggered by PINK1-induced phosphorylation of S442 of Mfn2." (PMID 37508561, 2023). "Our findings thus delineate the potential contributions of MFN2 and UCP4 to multiple diseases and particularly to the regulation of calcium homeostasis in A549 lung cancer cells." (PMID 36877954, 2023). "Previous research studies have reported that mitochondrial refusion by the overexpression of Mfn-2, a mitochondrial fusion protein, or inhibition of Drp-1, a mitochondrial fission protein, could lead to a decrease in cell proliferation and an increase in apoptosis in lung cancer." (PMID 35873543, 2022). "Indeed, our laboratory has found upregulated expression of DRP1 in both PAH and cancer cells with a parallel decrease in the expression of MFN2 in both PAH PASMC and lung cancers." (PMID 36819102, 2023). "Similarly, the DRP1/MFN2 ratio was increased in lung cancer patient tumor tissue, and DRP1 knockdown or inhibition blocked cell cycle progression in lung cancer cells." (PMID 34069047, 2021). "Collectively, our findings provide information helpful for clarifying the coregulatory mechanism of MFN2 and UCP4, which may regulate intercellular calcium homeostasis through PINK1‐mediated mitophagy or ER–mitochondria tethering and thereby affect the biological properties of lung cancer cells." (PMID 36877954, 2023). "Thus, MFN2 and UCP4 may be prospective therapeutic targets for lung cancer therapy." (PMID 36877954, 2023).
axonal neuropathy (23 papers, 2011 to 2026). Any nerve disorder affecting the axon of a nerve. "Charcot-Marie-Tooth disease type 2 A (CMT2A) is an inherited axonal neuropathy linked to mutations in MFN2, a key regulator of mitochondrial dynamics." (PMID 41932155, 2026). "For example, the MFN2 D210V variant has myopathy phenotypes in a three-generational case study, which has accompanying axonal neuropathy." (PMID 40175090, 2025). "Impairments in mitochondrial dynamics are linked to genetic neuropathies, with pathogenic variants in MFN2 that are typically associated with the axonal peripheral neuropathy Charcot–Marie–Tooth disease subtype 2A (CMT2A)." (PMID 40175090, 2025). "In a manner similar to INF2, MFN2, encoding a mitochondria outer-membrane protein enriched at ER-mitochondria contact sites, causes an axonal neuropathy (CMT2A2) associated with disruption of ER-mitochondria interactions and mitochondrial trafficking." (PMID 37491439, 2023). "Charcot-Marie-Tooth disease type 2A (CMT2A) is an axonal neuropathy caused by mutations in the mitofusin 2 (MFN2) gene." (PMID 36287202, 2022). "Autosomal recessive pathogenic variants in MFN2 gene have been identified in 29 patients, many of which presented with severe axonal neuropathy." (PMID 33578638, 2021). "More than 100 mutations within the gene encoding mitofusin 2 (MFN2) have been attributed to subtype 2A of Charcot–Marie–Tooth disease, the most common heritable axonal neuropathy." (PMID 30840087, 2019). "MFN2 mutations cause axonal neuropathy, with associated lipodystrophy only occasionally noted, however homozygosity for the p.Arg707Trp mutation was recently associated with upper body adipose overgrowth." (PMID 28414270, 2017). "Nerve conduction studies suggested an axonal neuropathy and molecular testing identified a previously reported pathogenic variant c.1090C > T, p.(Arg364Trp) in the MFN2 gene." (PMID 28063088, 2017). "Exome sequencing in the family trio was undertaken and directly interrogated to look for mutations in MFN2, given the known association of MFN2 with axonal neuropathy, and its recently reported association with MSL." (PMID 28414270, 2017). "Recently, we detected a novel mutation within the GTPase domain of MFN2—p.Arg274Trp (c.820C>T)–in a patient with early-onset CMT2A in which peripheral axonal neuropathy coexists with mild mental retardation." (PMID 28076385, 2017). "In one particular subtype of CMT2A, referred to as hereditary motor and sensory neuropathy type 6 (HMSN6), dominant MFN2 mutations result in visual failure secondary to optic atrophy in addition to the more typical axonal peripheral neuropathy." (PMID 27696015, 2016). "Although loss of MFN2 induces axonal neuropathy, the detailed mechanism by which MFN2 deficiency results in axonal degeneration of human spinal motor neurons remains largely unknown." (PMID 34602978, 2021). "We identified two pathogenic missense MFN2 variants (p.Arg280His, p.Arg259Cys) and a likely pathogenic MFN2 p.Thr206Ala variant in three probands with African ancestry and CMT2 (axonal neuropathy)." (PMID 37712079, 2023). "Charcot–Marie–Tooth disease type 2A (CMT2A) is a rare inherited axonal neuropathy caused by mutations in MFN2 gene, which encodes Mitofusin 2, a transmembrane protein of the outer mitochondrial membrane." (PMID 35418194, 2022). "Charcot–Marie–Tooth disease type 2A (CMT2A), arising from mitofusin 2 (MFN2) gene mutations, is the most common inherited axonal neuropathy affecting motor and sensory neurons." (PMID 32856204, 2020). "We recently identified a mutation within GTPase domain of MFN2, p.Arg274Trp (c.820C>T), in a patient with early-onset CMT2A with peripheral axonal neuropathy, as coexisting with mild mental retardation." (PMID 28076385, 2017). "A heritable human axonal neuropathy, Charcot-Marie-Tooth disease-2A2 (CMT2A2), is caused by MFN2 mutations." (PMID 21526202, 2011).
axonal neuropathy (continued). "Mutations in the MFN2 (mitofusin 2) and OPA1 genes, both involved in mitochondrial transport and/or fusion, cause two hereditary neurodegenerative disorders, respectively an axonal peripheral neuropathy (Charcot-Marie-Tooth Type 2, CMT2) and the dominant optic atrophy (DOA)." (PMID 31096646, 2019).
Hyperglycemia (22 papers, 2018 to 2025). An increased concentration of glucose in the blood. "Kowluru and colleagues reported that hyperglycemia alters mitochondrial dynamics, reducing the fusion protein Mitofusin 2 (Mfn2) and increasing the fission protein Dynamin-Related Protein 1 (Drp1), resulting in mitochondrial fragmentation." (PMID 41465114, 2025). "Mitochondrial disruption due to hepatocellular specific loss of MFN2 exacerbated NAFLD progression, inflammation, and hyperglycemia in mice fed with a high fat diet." (PMID 37284220, 2023). "In parallel, the mRNA level of the Ppargc1a and Mfn2 genes in fibroblasts exposed to hyperglycemia was reduced." (PMID 37569860, 2023). "Mitochondrial fragmentation is increased and the expression of Mfn2 is downregulated in retinal capillary cells and in hyperglycemia." (PMID 37415667, 2023). "Regulation of acetylation prevents hyperglycemia-induced reduction in the GTPase activity of Mfn2 and increase in mitochondrial fragmentation." (PMID 37415667, 2023). "Altogether, the results revealed that hyperglycemia-induced reduction of Mfn2 expression was related to glomerular damage and podocyte injury in DKD." (PMID 34988075, 2021). "The overactivated UPR branches such as PERK and ATF6 in hyperglycemia-treated cardiomyocytes can be alleviated by reducing MFN2 expression, and downregulation of MFN2 could attenuate mitochondrial dysfunction and ER-stress induced cardiomyocytes apoptosis." (PMID 37215098, 2023). "Similarly, it has been shown that hyperglycaemia increases the expression of fission proteins (e.g. dynamin‐related protein 1) and reduces the expression of fusion proteins (e.g. mitofusin 2 and Opa1)." (PMID 33453124, 2021). "Consistent with Mfn2, Dnmt inhibitors also restored hyperglycemia-induced elevation in 5mC at Mlh1 promoter DNA and decrease in its gene transcripts; the values in PC-GC/Aza or PC-GC/D-si or PC/Aza or PC/D-si groups were not different from those in Norm or GC groups." (PMID 32313015, 2020). "We detected the ubiquitination level of Mfn2 by immunopreipitation, which showed that exogenous H2S could increase the ubiquitination level of Mfn2 under hyperglycemia and hyperlipidemia." (PMID 32257541, 2020). "At the organelle level, chronic hyperglycemia disrupts mitochondrial homeostasis by upregulating the pro-fission protein dynamin-related protein 1 (Drp1) while downregulating the fusion regulator mitofusin 2 (Mfn2), ultimately leading to mitochondrial fragmentation." (PMID 40864768, 2025). "Of note, mitochondrial fragmentation induced by hepatocyte-specific deletion of the mitochondrial fusion protein mitofusin 2 (Mfn2) exacerbates NAFLD progression, inflammation and hyperglycemia in high-fat diet-fed mice." (PMID 33276146, 2021). "In addition, a common feature of mitochondria in hyperglycemia is fragmentation due to the activity of DRP1 and the downregulation of MFN2." (PMID 37760030, 2023). "Moreover, a study in ischemic brain has shown that hyperglycemia of T2DM produced a fragmented state, increasing Drp1 and decreasing Mfn2 and Opa1 levels, with alterations in the regulation of mitochondrial bioenergy." (PMID 32927647, 2020).
Alzheimer disease (21 papers, 2017 to 2025). A progressive, neurodegenerative disease characterized by loss of function and death of nerve cells in several areas of the brain leading to loss of cognitive function such as memory and language. "In fact, production of amyloid β-peptide (aβ), the main component of amyloid plaques causative of Alzheimer’s disease, was found to be decreased upon knockdown of MFN2." (PMID 31156446, 2019). "β-Amyloid (Aβ) protein was decreased in MFN2-impaired cells, indicating that the regulation of MFN2 might be associated with Alzheimer’s disease." (PMID 37550059, 2023). "Moreover, a role of MUL1 in the degradation of MFN2 was suggested in the context of dopaminergic (DA) neuronal loss, closely related to Parkinson’s and Alzheimer’s diseases." (PMID 31156446, 2019). "In neurons, MFN2 also plays a tissue-specific role in regulating mitochondrial axonal transport; its dysfunction, which causes energy failure, has been correlated to the pathogenesis of common neurodegenerative diseases, such as Alzheimer’s disease (AD) and Parkinson’s disease (PD)." (PMID 38007410, 2023). "Increasing evidence suggests a possible link between MFN2 deregulation and Alzheimer’s disease (AD)." (PMID 29491355, 2018). "Moreover, several studies have provided evidence implicating MFN2 in Alzheimer’s disease and amyotrophic lateral sclerosis (ALS)." (PMID 37550059, 2023). "Mfn2 could attenuate mitochondrial damage, cellular oxidative stress, and apoptosis in the animal models of cerebral ischemia-reperfusion (IR) injury and Alzheimer disease." (PMID 36531208, 2022). "Interestingly, downregulated protein expression of mitofusin 2 was also observed in frontal cortex and hippocampus of Alzheimer’s disease patients." (PMID 33257649, 2020). "Indeed, the frontal cortex of Alzheimer’s disease patients displays a reduction in MFN2 levels, as well as the hippocampal neurons of post-mortem patients, which is recapitulated in Alzheimer’s disease models." (PMID 31156446, 2019). "In addition to CMT, links have been made between MFN2 dysregulation and both Parkinson’s and Alzheimer’s diseases." (PMID 31156446, 2019). "Additionally, we demonstrate that some of these dysregulations, such as diminished DLP1 levels and its mitochondrial localization, as well as reduced STOML2 and MFN2 fusion protein levels, take place in fibroblasts from sporadic Alzheimer's disease patients." (PMID 29201274, 2017). "MFN2 and UCP4 play a coregulatory role in numerous disorders, including nonalcoholic fatty liver disease (NAFLD), Parkinson's disease, Alzheimer's disease (AD), and Huntington's disease." (PMID 36877954, 2023). "Pretreatment with SS-31 also reversed alterations in the expression of the mitochondrial proteins dynamin-related protein (DRP) 1, FIS1, mitofusin (MFN) 1, MFN2, and OPA1 in Alzheimer disease." (PMID 34221235, 2021).